TREM1 (triggering receptor expressed on myeloid cells 1)
Diseases named in the same sentence as TREM1 in open-access papers (continued):
Sharing a sentence is not in itself a finding about the gene and the disease.
lymph node metastasis (1 paper, 2021). "Notably, high TREM-1 expression was significantly associated with lymph node metastasis and advanced T classification." (PMID 34122331, 2021).
lymphedema (1 paper, 2022). Excess fluid collection in tissues, causing swelling. "We thus evaluated the effects of pharmacological blockade of Trem1 using murine LR12 (mLR12) in a widely used mouse tail model of lymphedema." (PMID 35725971, 2022). "Pharmacological blockage of TREM1 using LR12 could serve as a promising medical therapy for treating lymphedema." (PMID 35725971, 2022). "Together, these results suggested that the pharmacological blockage of Trem1 using mLR12 could significantly reduce inflammation and fibrosis, thereby alleviating the lymphedema in mice." (PMID 35725971, 2022). "In vivo experiments in mice suggested that pharmacological blockage of TREM1 using LR12 could serve as a promising medical therapy for treating lymphedema." (PMID 35725971, 2022). "Pharmacological blockage of Trem1, an immune receptor predominantly expressed by the pro-inflammatory macrophages, using murine LR12, a dodecapeptide, could significantly alleviate lymphedema in a mouse tail model." (PMID 35725971, 2022).
metastatic tumor (1 paper, 2022). "Once more, TREM-1 was expressed at significantly higher level in primary or metastatic tumor tissues than in non-tumoral colonic tissue (assessed by RT-qPCR), suggesting that TREM-1 was related to progression and metastasis in human CRC." (PMID 35875168, 2022).
microcephaly (1 paper, 2023). A congenital or acquired developmental disorder in which the circumference of the head is smaller than normal for the person's age and sex. "In this study, TREM1 rs2234246 and IL4 rs224325 in mothers infected with ZIKV during pregnancy was found to be associated with the occurrence of CZS microcephaly and the SNP CXCL10 rs4508917 and CXCL8 rs4073 in their children with presence of CZS microcephaly." (PMID 36859461, 2023).
non-alcoholic fatty liver (1 paper, 2023). A benign form of fatty non-alcoholic fatty liver disease where the disease has not yet progressed to the inflammation of liver. "MMP9 and TREM1 were identified as hub genes in PCOS patients with non-alcoholic fatty liver (NAFLD)." (PMID 37537636, 2023).
obstetric disorder (1 paper, 2024). Disorder associated with pregnancy, childbirth, and puerperium. "Recently, as more researchers have begun to explore the role TREM1 plays in obstetric disorders, TREM1 have been reported to be over-expressed in the third-trimester placenta and maternal serum of PE in several studies." (PMID 39295860, 2024).
oligodendroglioma (1 paper, 2024). A well-differentiated (WHO grade II), diffusely infiltrating neuroglial tumor, typically located in the cerebral hemispheres. "The incidence of 1p/19q codeletion was reduced with increasing TREM1 expression, which is a genomic characteristic of oligodendroglioma." (PMID 38370418, 2024).
ovarian dysfunction (1 paper, 2023). The inability of the ovaries to function. "Among the genes we identified through coexpression of three datasets, PNPLA3, MVD, MMP9, oncostatin M (OSM), LCK, triggering receptor expressed on myeloid cells 1 (TREM1), FADS2, proprotein convertase subtilisin/kexin type 9 (PCSK9), and C3 are involved in lipid metabolism and ovarian dysfunction." (PMID 37537636, 2023).
ovarian tumor (1 paper, 2025). "In this study, we firstly aimed to explore TREM1 expression patterns in ovarian tumor as well as their association with prognosis of survival." (PMID 39744496, 2025). "Overall, the differences in the results of these studies prompted us to investigate the interaction between TREM1 in ovarian tumors and the immune microenvironment." (PMID 39744496, 2025). "Therefore, we hypothesized that the pathways modulated TREM1 could affect the immune microenvironment of the ovarian tumors and thus influencing the biological behavior of carcinomas." (PMID 39744496, 2025). "Therefore, TREM1 could be a promising biomarker and novel therapeutic target for ovarian tumors." (PMID 39744496, 2025).
peripheral nerve injury (1 paper, 2021). Injury to a peripheral nerve. "Peripheral nerve injury activated a characteristic set of signaling pathways in both sexes, including HMGB1 Signaling, TREM1 signaling, IL-6 Signaling, IL-17 Signaling, Integrin signaling, HIF1α Signaling, Oxytocin Signaling, and ILK Signaling." (PMID 34966260, 2021).
pneumococcal pneumonia (1 paper, 2019). A febrile disease caused by STREPTOCOCCUS PNEUMONIAE. "The amelioration of inflammatory responses in the lung during pneumococcal pneumonia by ibrutinib may also result from inhibition of other Btk-dependent receptors that regulated S. pneumoniae-induced lung inflammation, including TLR4, TLR9, TREM-1 and NLRP3." (PMID 30646846, 2019).
Primary Immunodeficiency (1 paper, 2015). "RFXANK (primary immunodeficiency signaling) and CIITA (class II major histocompatibility complex transactivator involved in Antigen Presentation Pathway, Primary Immunodeficiency Signaling and TREM1 Signaling) were other high scoring molecules." (PMID 26302420, 2015).
renal clear cell carcinoma (1 paper, 2023). "In Immunohistochemical staining, we found that the expression of TREM-1 was significantly upregulated with increasing tumor grade in renal clear cell carcinoma, and elevated TREM-1 expression was associated with poor prognosis." (PMID 37217993, 2023). "Immunohistochemical staining was used to detect the expression of TREM-1 in renal clear cell carcinoma tissues." (PMID 37217993, 2023).
salmonellosis (1 paper, 2021). Infections with bacteria of the genus salmonella. "It has been reported that inhibition of the proteasome suppresses TREM-1 expression Interestingly, our previous study demonstrated that proteasome pathways were involved in SpvB-relevant salmonellosis." (PMID 33475464, 2021).
schistosomiasis (1 paper, 2023). An infectious disease caused by parasitic trematodes of the genus Schistosoma that colonize human blood vessels and release eggs that can cause granulomatous reactions leading to acute (swimmer's itch or acute schistosomiasis syndrome) or chronic disease. "Therefore, TREM1 may regulate the polarization of M1 macrophages during the course of schistosomiasis." (PMID 37430471, 2023).
skin cutaneous melanoma (1 paper, 2023). "We further evaluated the in vivo efficacy of the small molecule TREM1 inhibitor VJDT against a human skin cutaneous melanoma PDX model." (PMID 37651197, 2023).
steatosis (1 paper, 2022). Increased lipid within the cytoplasm of cells. "As the inhibitory peptide of TREM-1, GF9 attenuated TREM-1 expression and diminished production of proinflammatory cytokines, resulting in decreased steatosis and tissue damage in the liver." (PMID 36110326, 2022).
tendinopathy (1 paper, 2016). "The concomitant increase in the expression of TREM-1, RAGE and HMGB1 with respect to inflammation associated with glenohumeral arthritis and sterile inflammation signifies the involvement of these molecules in tendinopathy." (PMID 27792788, 2016).
infection (119 papers, 2008 to 2026). The state of being infected such as from the introduction of a foreign agent such as serum, vaccine, antigenic substance or organism. "Transcriptomicprofiling (RNA-seq) of peripheral blood mononuclearcells (PBMCs) demonstrated that genes involved in the TREM-1 activationwere upregulated during EV-A71 infection, which was associated witha poor prognosis." (PMID 39959083, 2025). "We found that in comparison to the WT, infection with the ▵vapC12 strain enhanced the expression of genes that encode proteins implicated in neutrophil-mediated immunity in the host (Cxcl2, Trem1, S100A8/A9 and Ccl3)." (PMID 38515752, 2024). "TREM-1 signaling has already been associated with host defense during the early stages of infection with highly pathogenic Streptococcus suis." (PMID 37854591, 2023). "Pathways of interest associated with WT infection included “Th17 vs Th1,” “Th17 vs Naive,” and “TREM1 signaling” and revealed that signatures associated with immune responses to extracellular pathogens are present in the lamina propria." (PMID 33529199, 2021). "We found that both granulocytes and monocytes were recruited after infection in the murine lungs although cell recruitment was affected in the TREM1–deficiency setting." (PMID 33525982, 2021). "TREM1 deficiency in mice, increased susceptibility to infection in an immunosuppressed murine model of IPA." (PMID 33525982, 2021). "Transcriptome group 1 (CAMP, CD14, FN1, TREM1) encodes for proteins that relate to acute response to infection, in particular to the LPS/TLR4 signaling pathway." (PMID 32325790, 2020). "Infected MoTB-127 were unable to express genes associated with infection control, and displayed alterations in myeloid effector function associated with differentiation, endocytosis, phagosome maturation, and the TREM1 signaling pathway." (PMID 32391286, 2020). "Here, TREM‐1 knock‐out (Trem‐1−/−) mice were used to inhibit TREM‐1 signalling to evaluate its role in inflammatory reactions after a highly pathogenic LPS infection in mice uteri." (PMID 31365951, 2019). "The characteristics of these ligands for TREM-1 provided an image of how TREM-1 signaling can be activated to control infection or cause severe disease." (PMID 29619033, 2018). "In this context, mice deficient in TREM1 exhibit reduced inflammation and lesion size upon infection by L. major, suggesting a pathogenic impact of TREM-1 signaling." (PMID 29670621, 2018). "The finding that both C/EBPε KO mice and Trem1/3 double KO mice exhibit increased susceptibility to infection indicates their overlapping function towards innate immunity mediated by granulocytes." (PMID 28440307, 2017). "In this study however, we observed, using the same infection model, that survival of B. pseudomallei-infected TREM-1-deficient mice was similar to WTs." (PMID 27253382, 2016). "Furthermore,the higher expression of Trem1 observed during in vitro infection was associated with genes involved inthe pyroptosis pathway rather than apoptosis, strongly suggestingthat TREM-1 plays a role in NoV pathogenesis." (PMID 39959083, 2025). "In addition, the expression of pathways, such as dendritic cell maturation, acute-phase response signaling, and TREM1 signaling, associated with early immunity suggests that B. canis has been active in the host since early infection." (PMID 33829052, 2021). "TREM1 deficiency increased susceptibility to infection in the immunosuppressed murine host." (PMID 33525982, 2021). "In addition, TREM1 can be secreted as a soluble form (sTREM1), and therefore it has been utilized as a diagnostic marker for inflammatory processes including infections." (PMID 33525982, 2021). "Thus, TREM-1 signaling pathway is an important mediator of inflammatory responses associated with EV-D68 infections." (PMID 34887856, 2021).
infection (continued). "TREM-1 is a pattern-recognition receptor expressed on neutrophils and monocytes that is implicated in the development and amplification of the early inflammatory response to infection and injury." (PMID 29282483, 2018). "Furthermore, TREM-1 has been recently linked to trans-epithelial migration of neutrophils after infection with P. aeruginosa." (PMID 27253382, 2016). "Moreover, weight loss in Trem1−/− mice was significantly attenuated and Trem1−/− mice further exhibited reduced levels of IL-6 in bronchoalveolar lavage fluid (BALF) at 10 days post infection." (PMID 24453980, 2014). "Importantly, while immune-associated pathologies were significantly reduced, Trem1−/− mice were equally capable of controlling infections with L. major, influenza virus, but also Legionella pneumophila as Trem1+/+ controls." (PMID 24453980, 2014). "Therefore, it is possible that the interaction between TREM-1 on neutrophils with the GP protein during infection contributes to the “cytokine storm” associated with lethal filovirus disease." (PMID 25505454, 2014). "By contrast, the pool of genes induced during ΔF2 Nig06 infection is mainly involved in the mounting of an immune response: Trem1, Kng1, Nfatc2ip and Xcr1 are particularly implicated in mediation of inflammation, cytokine induction and leukocyte chemoattraction." (PMID 23469251, 2013). "More precisely, infections caused by Streptococcus pneumoniae, Sthaphylococcus aureus and Haemophilus influenzae were accompanied by greater levels of sTREM-1 and by greater expression of TREM-1 on neutrophils than infections caused by other pathogens." (PMID 20920231, 2010). "In addition, as demonstrated in sepsis, the expression levels and timing of different TREM-1 ligands may vary depending on the stage of sepsis and type of infection, further increasing risk of failure of ligand-dependent TREM-1 inhibitors." (PMID 39737196, 2024). "Since the rapid kinetics of this model hardly allowed to simultaneously look at beneficial effects of the Trem1 deficiency on immune-mediated tissue damage or to assess potential adverse consequences for the priming of adaptive immune responses, we chose the Leishmania major infection model." (PMID 24453980, 2014). "The TREM-1-TLR-NLR forms a tightly coordinated regulatory network that governs innate immune responses during infection, tissue injury, and chronic inflammation." (PMID 41226426, 2025). "This adds a level of complexity; therefore, biomarkers more associated with infection than inflammation had a discriminative advantage over the inflammatory markers, e.g., IL-6, IL-8, CRP, PCT, lactate, TREM-1, and uPAR." (PMID 39857101, 2025). "Despite this, their data showed a similar pattern to that observedin the GSE94821 study regarding the expression dynamics of Trem1 during the first 8 h of infection." (PMID 39959083, 2025). "The findings revealed that tacrolimus treatment reduced corneal damage in the early stages of infection, decreased TREM-1 expression in infected corneas, and attenuated the expression of inflammatory factors." (PMID 41226426, 2025). "Triggering receptor expressed on myeloid cells 1 (TREM-1) is an innate immune receptor that plays an important role in the amplification of the innate immune response to infection by stimulating the release of pro-inflammatory cytokines." (PMID 38254697, 2024). "Triggering Receptor Expressed on Myeloid Cells-1 (TREM1) was an inducer of pro-inflammatory molecules and reactive oxygen species (ROS) in response to damage or infection." (PMID 39596030, 2024). "It is believed that the upregulated expression of TREM1 in response to infection will augment inflammatory response not only remove the pathogens but also aggravate the organs damage." (PMID 37700323, 2023). "Lastly, neutrophils phagocytose residual debris; Neutrophils express Triggering Receptor Expressed on Myeloid Cells 1 (TREM1) which can augment the immune response to infection and trigger an inflammatory cascade." (PMID 35666753, 2022).
infection (continued). "TREM-1/3-/- mice had increased mortality and bacterial dissemination after infection with Streptococcus pneumoniae and Klebsiella pneumoniae, despite infected primary TREM-1/3-/- macrophages having decreased cytokine release." (PMID 35784361, 2022). "TREM1 is an enhancer of pro-inflammatory innate immune responses and plays an important role during infection." (PMID 36189218, 2022). "In both in vitro and in vivo studies, infection with Aspergillus fumigatus (A. fumigatus) has been shown to upregulate TREM-1 expression on corneal epithelial cells." (PMID 36273145, 2022). "TREM-1-/- mice also had reduced morbidity after infection with influenza A virus, measured by body weight and temperature, and decreased IL-6 in bronchoalveolar lavage." (PMID 35784361, 2022). "Confirming the observations made above, infection with all three L. major induces (cluster 1) neutrophil recruitment, myeloid activation, and production of cytokines/chemokines (e.g. Trem1, Trem3, C5ar1, Ltf, Ptgs2, Ccl2, Ccl12, Ccl17, etc.)." (PMID 34972189, 2021). "The production of CXCL1, IL-1β, TNF, and IL-6 was decreased in the lungs of Trem1−/- mice at early stages on the infection (2 dpi)." (PMID 33525982, 2021). "The results showed that the highly activated TREM-1 was involved in inflammatory cytokines production during EV-D68 infection." (PMID 34887856, 2021). "In vivo, the role of TREM1 has been characterized in experimental murine models of microbial sepsis, infection with influenza virus, Leishmania major and other bacterial infections, in which suppression of TREM1 signaling conferred significant protection." (PMID 33525982, 2021). "Especially in the case of infection with P. aeruginosa, TREM1 contributed to this through mechanisms involved in the migration of neutrophils for the removal of pathogens." (PMID 33829052, 2021). "The soluble form of TREM-1 (sTREM-1) has been detected in biological samples, such as plasma, during infection and inflammation processes." (PMID 34960790, 2021). "The expression of TREM-1 will increase after infection, and some membranous TREM-1 is shed into the systemic circulation through the activation of metalloproteinases." (PMID 32508526, 2020). "Triggering receptor expressed on myeloid cells-1 plays an essential role on S. suis clearance, and TREM-1 blockage alone cannot rescue the host from the infection." (PMID 29619033, 2018). "At the early stage of infection, TREM-1 recognizes the natural ligands (such as surface actin on the platelets) and activate neutrophils, which is essential for bacterial clearance." (PMID 29619033, 2018). "Infection with S. suis also induced TREM-1 expression, indicating the signaling involved in this infectious disease." (PMID 29619033, 2018). "During an infection, the expression of membrane-bound TREM-1 is increased and the level of sTREM-1 is elevated in plasma, bronchoalveolar lavage fluid and spinal fluid." (PMID 29282483, 2018). "Upon infection of peripheral blood-isolated neutrophils with the parasites for 30 min in vitro, gene expression of TREM-1, DAP12, and IL-8 was found to be higher compared to unexposed neutrophils." (PMID 29201022, 2017). "By regulating Trem1 transcription in steady state granulopoiesis, C/EBPε prepares granulocytes to respond to infection." (PMID 28440307, 2017). "Mice were killed at 0, 24, and 72h after infection (i.e., directly before the first predicted death), and TREM-1/-2 mRNA expression was determined in lungs and livers." (PMID 27253382, 2016). "The role of TREM-1 has mostly been acknowledged from acute infection models where blockade of TREM-1 conferred significant protection." (PMID 27762264, 2016). "In the early phase of infection, the engagements of Pattern Recognition Receptors (PRRs) by microbial components induce up-regulation of TREM-1." (PMID 27116911, 2016).